BECN1 (beclin 1)
Diseases named in the same sentence as BECN1 in open-access papers (continued):
Sharing a sentence is not in itself a finding about the gene and the disease.
cancer (continued). "Moreover, it has been reported that cancer cells sustain hypoxia by upregulating the BCL2 interacting protein 3 (BNIP3)/BNIP3-like (BNIP3L), which in turn induces BECLIN-1 dependent autophagy by destabilizing Bcl-2-BECLIN-1 complex." (PMID 40917756, 2025). "Furthermore, an upregulation of autophagy markers beclin‐1, p62, and LC3B‐II has been observed in cachectic rodent models and in the hearts of cancer survivors." (PMID 40985218, 2025). "Moreover, the overexpression of Becn1 resulted in an increased expression of LC-3II and CDK 4 while decreasing cyclin E expression in the cancer cell lines." (PMID 40723786, 2025). "Similarly, pterostilbene restores autophagic activity in cisplatin-resistant OSCC cells by activating autophagy-related genes, including ATG5, ATG7, and Beclin-1, through modulation of the AKT pathway, leading to enhanced cancer cell death." (PMID 39840028, 2024). "Additionally, the expression of cancer marker BIRC2/cIAP1 (p = 0.002) and autophagy marker Beclin-1 (p = 0.02) were observed in plasma-derived sEVs and PanNET tissue." (PMID 38596136, 2024). "Silencing the autophagy genes, such as ATG5, ATG7, and BECN1, could inhibit the DAMP release from mitoxantrone or oxaliplatin-treated cancer cells and subsequently impair the antitumor immunity." (PMID 36814780, 2023). "The involvement of BECN1 in the induction of autophagy seems to also be related to lipid metabolism through fatty acid β-oxidation (FAO) and subsequent entry into the TCA cycle in myeloid leukemia and colon and gastric cancer." (PMID 37887330, 2023). "It was indeed reported that Beclin-1, but also ATG5 and ATG3, are caspase-8 substrates in vitro, and that after death receptor activation in several cancer cells, the subsequent downregulation of autophagic flux is partly due to caspase-8-dependent cleavage of these autophagic proteins." (PMID 36418547, 2023). "Hydrogen peroxide (H2O2) and 2–methoxyestradiol (2–ME) induced autophagic cell death in various cancer cells, which was inhibited by 3–MA or the deletion of Beclin–1 or Atg7 but not by pan caspase inhibitor Z–VAD." (PMID 37762548, 2023). "In this study, we found that the mRNA level of Beclin-1 is significantly elevated in cancer tissue samples as compared to adjacent normal tissue and non-squamous NSCLC patients with high Beclin-1 are associated with high mortality rates and shorter PFS." (PMID 36401689, 2022). "Previously studies have demonstrated that the dysfunction of Beclin 1, a major regulator of autophagy and a core component of the class III PI3K complexes, may lead to diseases as well as cancer." (PMID 36401689, 2022). "Two important autophagy genes, Beclin-1 and LC3, have been reported in several human cancers." (PMID 35768796, 2022). "illuminated that miR-423-3p, which indicated a poor prognosis in GC, was highly expressed in GC tissues and promoted cancer progression; however, this effect was blocked by knockdown of the ATG7, suggesting the oncogenic role of miR-423-3p via beclin-1-mediated autophagy." (PMID 36353541, 2022). "In metastatic HCC, miR-30a mediates Beclin 1 and Atg5-dependent autophagy, which confers anoikis resistance of HCC cells 50, suggesting important roles of miRNAs in the regulation of autophagy and anoikis resistance in cancer." (PMID 33995620, 2021). "MiRNA MIR17 with low expression could negatively regulate target genes BECN1 and CD28 to promote the proliferation of cancer cells and inhibit autophagy, apoptosis, and the immune response." (PMID 33802957, 2021). "Its target genes BECN1 would induce autophagy and E4BP4 suppressed by TF SMAD3 could promote cancer progression by reducing NK cell development." (PMID 33802957, 2021). "Also, knockdown of Beclin-1 (BECN1), a mediator of autophagy, attenuates anoikis resistance, thereby inhibiting the spheroid formation of cancer cells under anchorage-independent conditions." (PMID 33435156, 2021).
cancer (continued). "Finally, we proposed in 2020 an overview of the role of autophagy, and namely its pivotal Beclin-1 protein, in CCND1 degradation, as a possibly actionable mechanism for G1/S cell cycle arrest in cancer." (PMID 34445095, 2021). "Significantly, the formation of a BECN1-PtdIns3K complex was only observed in cancer cells in response to starvation, but not against ferroptotic stimulus." (PMID 34007410, 2021). "However, the poor prognosis of various cancer patients is closely related to the high expression of autophagy-related LC3 and Beclin-1 protein." (PMID 34675987, 2021). "Further considerations emerge, in addition, from the analysis of several existing data indicating additional non-autophagic roles of beclin-1 expression in cancer." (PMID 33330070, 2020). "Our data indicate that knockdown of BECN1 has no influence on cancer cell growth but markedly increases mobility and invasion." (PMID 32358527, 2020). "Mechanistically, phosphorylation of BECN1 at Ser90/93/96 through AMP-activated protein kinase (AMPK) promotes ferroptosis by binding to SLC7A11 and directly blocking the activity of system Xc-, contributing to cancer cell death." (PMID 33204324, 2020). "BCL-2/BECLIN-1-dependent autophagic cell death has not been thoroughly investigated in HDACi-treated cancer cells but is nevertheless presumed to mediate combined activation of both cell types in most cases." (PMID 31096697, 2019). "The only available data came from MDA-MB-231 and T47D cancer cell lines where DIM (1–10 μM) inhibited H2O2-induced autophagy, i.e., it inhibited the expression of Beclin-1 and reduced the percentage of cells exhibiting autophagy and conversion of LC3-I into LC3-II." (PMID 30778709, 2019). "Furthermore, JNK was also found to be involved in the autophagy of cancer cells by several mechanisms including upregulating the ATG5 expression, facilitating the Beclin-1 production, and triggering the dissociation of the Bcl-2/Beclin-1 complex." (PMID 30717138, 2019). "Additionally, CRBN inhibited TRAF6-induced ubiquitination of BECN1 (Beclin 1), and that induced autophagy activation in CRBNKD THP-1, CRBN-knockout (CRBNKO) H1299, and CRBNKO MCF7 cancer cells in response to TLR4 stimulation." (PMID 31620128, 2019). "BIF-1 proteins that are related to BECN1 have been observed to become abnormal or absent in variety of cancer types, such as colorectal and gastric cancer." (PMID 30400561, 2018). "LC3II (p < 0.05), LC3II/I (p < 0.01), and Beclin-1 (p < 0.05) increased in the liver by the C26 cancer without changes in p-ULK1Ser757 and P62 protein." (PMID 30713500, 2018). "The observed Beclin-1/LC3B/p62 IHC patterns, obtained from serial sections analysis, along with TEM findings are suggestive of a declined authophagic activity in preneoplastic lesions that was restored in full blown cancers." (PMID 28880214, 2017). "In conclusion, expression of autophagy-related proteins (beclin-1, LC3B, p62, and BNIP3) was higher in HCNs and HCCs compared to FNs and HCAs, respectively, and this could have implications in cancer therapeutics." (PMID 28819333, 2017). "As previously reported, both Beclin 1 and LC3B were expressed in most cancer tissues." (PMID 28938618, 2017). "On the other hand, cancer cells treated with PTX alone decreased the beclin-1 level which was not affected when cells were co-treated with PTX plus either inhibitor, in comparison with the control." (PMID 28915644, 2017). "Different from a previous report in cancer stem cells, rottlerin treatments did not alter protein levels of the autophagy regulator, beclin-1." (PMID 26849807, 2016). "Moreover, monoallelic loss of the essential autophagy gene BECN1 causes susceptibility to metabolic and promotes tumorigenesis, which is consistent with our observations that RNF216 could enhance BECN1 degradation dampening autophagy and contributing to cancer cells proliferation." (PMID 27203674, 2016).
cancer (continued). "Although RNF216 has several interaction partners, such as TLR4, RIP1, TRAF3 and BECN1, our data showed that only BECN1 was significantly upregulated in CRC cells in response to RNF216 knockdown, supporting that RNF216 contributes to cancer development by regulating autophagy." (PMID 27203674, 2016). "For example, methylation of BECN-1, a tumor suppressor gene, has been observed in BC, while methylation of ATG16L2, LC3A, ULK2, or BNIP3 has been suggested to be involved in the down-regulation of autophagy in other cancers." (PMID 26474850, 2015). "In addition, the JNK1 pathway was demonstrated to serve a pivotal role in regulating beclin-1 expression at the transcriptional level following ceramide-induced autophagy in human CNE2 and Hep3B cancer lines." (PMID 26622781, 2015). "Previous studies revealed that mammalian species fail to survive in the absence of Beclin-1 and develop cancers with the low expression of Beclin-1." (PMID 25877859, 2015). "The association of Beclin 2 and cancer has not been addressed, and the relationship between Beclin 2 and Beclin 1 expression and the outcomes of cancer patients have never been studied." (PMID 26506105, 2015). "The present study indicated that Beclin-1 and PTEN may be co-involved in the regulation of autophagy, and therefore affect the occurrence and development of cancer." (PMID 25789037, 2015). "An interesting non-canonical autophagic process characterized by a Beclin-1/Vps34-independent pathway was observed in MCF-7 cancer cells in response to resveratrol treatment." (PMID 25375374, 2014). "Similarly, we observed that JNK was involved in Beclin 1 expression, which then played a crucial role in protective autophagy in DHA-induced cancer cells." (PMID 24438216, 2014). "There has been increasing research into the effects of Beclin 1 on cancer progression in recent years, but no definite conclusions have been established." (PMID 24675697, 2014). "Seen from a different point, of the 32 patients that underwent CR as many as 24 were bearing a BECLIN 1-positive cancer and only 8 were bearing a BECLIN 1-negative cancer." (PMID 25136588, 2014). "Both Beclin 1 and BCL-2 have established roles in the development of cancer." (PMID 23840208, 2013). "In summary, our finding clearly demonstrated that SSE has anti-cancer activity via suppression of the Akt/mTOR signaling pathway through AMPK activation, which resulted in the down-regulation of Bcl-2 and up-regulation of Beclin-1." (PMID 24053190, 2013). "Beclin 1 and LC3, crucial genes for autophagy, are altered in several types of human cancer." (PMID 23420500, 2013). "Indeed, cancer cells sustain hypoxia by upregulating the BCL2 interacting protein 3 (BNIP3)/BNIP3-like (BNIP3L), which in turn induces Beclin-1 dependent autophagy by destabilizing Bcl-2-Beclin-1 complex." (PMID 40917756, 2025). "The interaction of GBMs with autophagy signaling pathways could affect key autophagy-regulating proteins, such as Beclin-1, LC3, mTOR, and AMPK (AMP-activated protein kinase), either enhancing or suppressing autophagy; thus, modulating the survival or death of cancer cells." (PMID 40429669, 2025). "In addition, omega-3 fatty acids induce cancer cell apoptosis by accumulating reactive oxygen species (ROS) and activating caspases, and also activate autophagy flux through SIRT1-mediated Beclin-1 deacetylation and AMPK pathway, thereby alleviating oxidative stress and inflammation." (PMID 40761352, 2025). "Moreover, by phosphorylating Beclin-1 at Ser90/93/96, PRKAA/AMPKα boosts the assembly of the Beclin-1-SLC7A11 complex, inhibits system xc−, and stimulates the resulting ferroptotic demise of cancer cells." (PMID 39650649, 2024). "Thus, natural polyphenolic compounds in the diet can trigger cancer cell death via various mechanisms through the canonical (Beclin-1 dependent) and non-canonical (Beclin-1 independent) routes of autophagy." (PMID 34361052, 2021).
cancer (continued). "In our study, autophagy and Beclin-1 expression were both increased in TACC1v25 overexpressing HNSCC lines with deceased cell proliferation, suggesting that TACC1v25 may be useful against a more aggressive cancer phenotype." (PMID 34897285, 2021). "Beclin-1 facilitated the interaction of protooncogene avian myelocytomatosis virus oncogene cellular homolog (cMyc) and its phosphatase PP2A, leading to dephosphorylation and degradation of c-Myc, resulting in decreased cell division and cancer cell proliferation." (PMID 33976943, 2021). "Natural polyphenolic substances, e.g., flavonoids and non-flavonoids, exert an antitumor action through the upregulation of cancer suppressors and autophagy mediated via signalling pathways that are both canonical (Beclin 1-dependent) and non-canonical (autonomous of Beclin-1)." (PMID 34680470, 2021). "Whether these events are important for autophagy regulation remains to be investigated, but the deletion of protease ICP10K, known for binding with Beclin 1, from the genome of HSV2, another vastly used gene therapy vehicle, triggers cell-specific apoptosis in cancer cells." (PMID 34298694, 2021). "Furthermore, functional experiments demonstrated that the effect of knockdown BECN1 on cancer cells was reversed by genetic or pharmacological inhibition of STAT3, strongly indicating that BECN1 is involved in CRC metastasis through regulation of STAT3 phosphorylation in CRC." (PMID 32358527, 2020). "In addition, the study also indicated that Beclin-1 gene knockout may promote EMT and carcinogenesis by activating the Wnt1 and NF-κB pathways resulting in cancer cell metastasis." (PMID 33050301, 2020). "In cancer cells under starvation, C-Jun N-terminal protein kinase 1 (JNK1) becomes activated and phosphorylates Bcl-2, disrupting the Bcl-2/Beclin-1 complex and promoting autophagy due to the activation of core autophagic components by isolated Beclin-1 as a response for cell protection." (PMID 33194736, 2020). "Based on the existing literatures, we find (a) coptisine exerted potential to be an anti‐cancer, anti‐inflammatory, CAD ameliorating or anti‐bacterial drug through regulating the signalling transduction of pathways such as NF‐κB, MAPK, PI3K/Akt, NLRP3 inflammasome, RANKL/RANK and Beclin 1/Sirt1." (PMID 31622015, 2019). "However, the immunopositive rate for LC3 A/B as well as Beclin 1 was not surprising, since they have been highly expressed in various types of cancer cells with autophagy-positive status." (PMID 30893939, 2019). "This indicated that monoallelic deletion in BECN1 gene might not fully reflect the protein expression of BECN1 in cancer cells." (PMID 31272261, 2019). "Expression of beclin-1 in cancer or stromal cells alone did not correlate with patient prognosis." (PMID 25955408, 2015). "Additionally, the death-associated protein kinase, DAPK, a protein that phosphorylates Beclin-1 thereby disrupting Beclin-1/BCL-2 complex and favoring autophagy, is another inducer of autophagy that is commonly silenced in different types of human cancers by methylation." (PMID 25328887, 2014). "However, the relationship between the level of Beclin 1 expression and cancer prognosis is not yet conclusive." (PMID 24675697, 2014). "Since we could not find the effect of OY on beclin-1 in this study, we are going to investigate the detailed mechanism of autophagy induced by OY in other cancer cells." (PMID 23573119, 2013). "The high levels of Beclin 1 observed in CH and CIRR tissues suggest a central role for autophagy as a stress-responsive pathway that may limit liver damage and interact with progression to cancer." (PMID 22928777, 2012). "Although the possibility that Beclin-1-induced autophagy can be a process to rescue cancer cells from As4O6-induced apoptosis could not be excluded, our finding suggested that ROS induced by As4O6 should lead to Beclin-1-induced autophagy." (PMID 21912568, 2012).
cancer (continued). "Another limitation is that we have not verified yet whether Beclin-1-induced autophagy is a critical mechanism for As4O6-induced cell death or a mechanism to rescue cancer cells from toxic damage." (PMID 21912568, 2012). "In addition, the expression levels of autophagy markers such as Beclin-1, ATG5, ATG7, and LC3II conversion were significantly higher in human tumors compared to adjacent nontumor tissues, demonstrating the correlation with upregulation of autophagy function in cancer cells." (PMID 33806593, 2021). "Carcinoma cells in tissues with stromal beclin 1 positivity had higher Ki-67 LI than those without its positivity (p = 0.042 for hot spot Ki67 and 0.0075 for overall average Ki67, N = 53), suggesting the correlation between stromal beclin 1 expression and carcinoma cell proliferation." (PMID 26984766, 2016). "It was demonstrated that ROS can induce autophagy through several distinct mechanisms involving Atg4-Atg8/LC3, Beclin-1, PI3K-Akt-mTOR, catalase, and the mitochondrial electron transport chain, which leads to both cell-survival and cell-death responses and could be selective toward cancer cells." (PMID 25891311, 2015). "The absence of beclin 1 (BECN1), one of the autophagy genes, is observed to widely occur in human cancer cases." (PMID 36814780, 2023). "LC3B and beclin-1, key autophagy proteins, were also not activated after treatment with AGK2 in this cancer." (PMID 35406775, 2022). "Higher levels of LC3, BECLIN 1, and p62/SQSTM1 proteins were found in specimens of CCAs at all steps of progression, from pre-invasive to invasive carcinomas, compared with non-neoplastic large bile duct and peribiliary gland tissues." (PMID 33925189, 2021). "Immunostaining for LC3A/B, Beclin-1 and AMBRA-1 were exclusively found in cancer cells, but not in surrounding stromal cells." (PMID 30893939, 2019). "Although AMPK is known as autophagy inducer in various kinds of cancers, OBE did not increase autophagy-related factors such as LC3B and beclin-1 in this study (Data not shown)." (PMID 31652886, 2019). "We found that the autophagy markers, Beclin-1 and LC3-I/II, were increased in paclitaxel-treated cancer cells, but not in docetaxel-treated cancer cells." (PMID 27263528, 2016). "The present data showed that, as opposed to in chondrocyte or cancer cells, the mRNA and protein expression of autophagy-related genes, LC3 and Beclin-1, showed no change in response to TNF-α and IL-1β." (PMID 26165348, 2015). "At gene level, Beclin-1, p-62, BNIP3, NIX/BNIP3L and TFEB mRNAs were not significantly modulated, while LC3B and PINK1 mRNA levels were increased and decreased, respectively, in cachectic cancer patients." (PMID 27459917, 2016).